USP17L15 (ubiquitin specific peptidase 17 like family member 15)
Description:
Deubiquitinating enzyme that removes conjugated ubiquitin from specific proteins to regulate different cellular processes that may include cell proliferation, progression through the cell cycle, apoptosis, cell migration, and the cellular response to viral infection.
Tractability: No criterion of Open Targets' tractability assessment is met for any kind of drug.
Gene: Protein-coding gene on chromosome 4 (9,234,385 to 9,236,046, forward strand). Ensembl gene ENSG00000223569.
Subcellular location: Nucleus; Endoplasmic reticulum
Pathways (Reactome):
Metabolism of proteins: Ub-specific processing proteases
Gene Ontology:
Molecular function: cysteine-type deubiquitinase activity
Biological process: regulation of apoptotic process; protein deubiquitination
Cellular component: endoplasmic reticulum; nucleus
Homologues: Paralogues in human: USP17L11 (95% identical), USP17L18 (95% identical), USP17L20 (95% identical), USP17L19 (95% identical), USP17L22 (95% identical), USP17L17 (95% identical), USP17L24 (95% identical), USP17L25 (95% identical), USP17L26 (95% identical), USP17L27 (95% identical), USP17L28 (95% identical), USP17L29 (95% identical), and 59 more.
Diseases named in the same sentence as USP17L15 in open-access papers:
USP17L15 is named in the same sentence as 1 disease in open-access papers, as found by Europe PMC text mining. Sharing a sentence is not in itself a finding about the gene and the disease. The quoted sentences say what the papers report.
psoriasis (1 paper, 2021). An autoimmune condition characterized by red, well-delineated plaques with silvery scales that are usually on the extensor surfaces and scalp. "Therefore, USP17L15 may be involved in the pathogenesis of psoriasis." (PMID 35126107, 2021).